TNNT1 (troponin T1, slow skeletal type)
Diseases named in the same sentence as TNNT1 in open-access papers (continued):
Sharing a sentence is not in itself a finding about the gene and the disease.
tumor (20 papers, 2014 to 2024). "mRNA vaccines encoding these tumor antigens (THBS2, FSTL3, TNNT1, BGN, CTHRC1, and NOX4) induce a cell-mediated immune response and humoral immune response that are beneficial for efficient clearance of cancer cells." (PMID 35127707, 2021). "Tnnt1 was highly expressed in tumor tissues and PTC cells of testosterone-treated mice." (PMID 37477865, 2024). "The study also examined TNNT1's effect on the tumour microenvironment and drug sensitivity in KIRC, complemented by in vitro TNNT1 knockdown experiments in KIRC cells." (PMID 38853457, 2024). "RT-qPCR and IHC indicated that the expression of GLS, NOX1, HOXC6, TNNT1 and PLA2G12B were up-regulated in tumor tissues, compared with those in normal tissues, and all of GLS, HOXC6, NOX1 and PLA2G12B were closely related with patient survival." (PMID 37333810, 2023). "Immune infiltration analysis revealed that the expression levels of TNNI3, TNNT1, ACTC1, and MYH11 were correlated with the level of immune cell infiltration and tumor purity." (PMID 36514150, 2022). "Six tumor antigens (THBS2, FSTL3, TNNT1, BGN, CTHRC1, and NOX4) were identified as potential therapeutic candidates for the anti-CRC mRNA vaccine that can be processed and presented by APCs to activate a robust immune response." (PMID 35127707, 2021). "Compared with those in the normal pancreas (GTEx + TCGA), CA9, TNNT1, CCL21, LY86, and CCL19 were all expressed higher in tumor tissues, except for FABP4, which was expressed lower in a tumor (p < 0.001)." (PMID 34777388, 2021). "In tumor-infiltrating I-MDSC, high gene signature comprising of TNNT1, NPL and CATSPER1 predicted poor OS rates in COAD patients." (PMID 33312958, 2020). "The expression levels of BIRC5, TK1, TNNT1 and MMP9 were found to be positively related to tumor recurrence after cystic resection." (PMID 25970782, 2015). "Furthermore, we found that TNNT1, ACTC1, and MYH11 expression levels were negatively correlated with tumor purity, while TNNI3 expression levels were positively correlated with tumor purity." (PMID 36514150, 2022). "The correlation between TNNT1 expression and tumor progression (TNM grade) or serum tumor marker CA19–9 might catch more attention on its potential application in diagnosis for GBC." (PMID 25970782, 2015). "Therefore, we investigated whether the expression of THBS2, FSTL3, TNNT1, BGN, CTHRC1, and NOX4 was correlated with immune cell infiltration levels in CRC via the Tumor Immune Estimation Resource (TIMER) database." (PMID 35127707, 2021).
cancer (19 papers, 2013 to 2025). A tumor composed of atypical neoplastic, often pleomorphic cells that invade other tissues. "TNNT1 is overexpressed in several cancers and linked to adverse outcomes, showing frequent upregulation mutations and abnormal methylation." (PMID 38853457, 2024). "TNNT1, the troponin T type 1 encoding gene, was up-regulated increasingly from cancer initiation to advanced stage." (PMID 30598639, 2018). "Troponin T1 (TNNT1) plays a crucial role in muscle contraction but its role in cancer, particularly in kidney renal clear cell carcinoma (KIRC), is not well-understood." (PMID 38853457, 2024). "We analysed TNNT1 expression in cancers using databases like TCGA and GTEx, assessing its prognostic value, mutation patterns, methylation status and functional implications." (PMID 38853457, 2024). "This study explores the expression, clinical significance and biological functions of TNNT1 in various cancers, with an emphasis on its involvement in KIRC." (PMID 38853457, 2024). "Functionally, TNNT1 connects to muscle and cancer pathways, affects immune infiltration and drug responses, and its overexpression in KIRC is associated with advanced disease and reduced survival." (PMID 38853457, 2024). "Recently, it has been reported that TNNT1 mRNA expression is higher in several cancer tissues, such as cervix, colon, lungs, ovaries, and testes, than in normal tissues, and is related to cell migration." (PMID 31557240, 2019). "Cancer tissues of cervix, colon, lungs, ovaries, and testes showed significantly elevated levels of TNNT1 expression as compared with the corresponding normal tissues." (PMID 28811571, 2017). "In the context of cancer, we demonstrated substantial expression of TNNT1 in cancer tissues of the cervix, colon, lungs, ovaries, and testes." (PMID 28811571, 2017). "However, the markers of invasion S100A4 and TNNT1 were found to be similar in both types of cancer at this stage of disease." (PMID 40433700, 2025). "Besides, knockdown of Tnnt1 expression can inhibit the cancer-promoting roles of testosterone in PTC cells." (PMID 37477865, 2024). "Also, this group used a TissueScan array technique and detected significant overexpression of TNNT1 in human cancers of the cervix, colon, lung, ovary, and testis compared to normal tissue." (PMID 29416706, 2018). "This is the first study to implicate a functional role for TNNT1 in cancer-related processes." (PMID 29416706, 2018). "According to our results and previous reports, TNNT1 seems to play multiple roles in cancer." (PMID 28811571, 2017). "Additionally, we demonstrated that TNNT1 mRNA expression is higher in several cancer tissues than in normal tissues." (PMID 28811571, 2017). "The study reported that the potential muscle-specific genes expressed in cancer cells were TNNI1, TNNT1, DES, TRDN, MYH6, MYH11, and MYH13." (PMID 36378654, 2022). "TNNT1's aberrant expression plays a significant role in tumorigenesis and immune modulation, highlighting its value as a prognostic biomarker and a potential therapeutic target in KIRC and other cancers." (PMID 38853457, 2024). "Analysis of the various cancers revealed that several putative REST target genes, including Polo Like Kinase 1 (PLK1), ADAM Metallopeptidase Domain 12 (ADAM12), Troponin T1 (TNNT1), and cell migration-inducing and hyaluronan-binding protein (CEMIP, KIAA1199) were highly dysregulated." (PMID 35177031, 2022). "Furthermore, the genes encoding cTnC (TNNC1; Id: COSG56773), fsTnC (TNNC2; Id: COSG65631), and all three TnT isoforms (TNNT1, Id: COSG65275; TNNT2, Id: COSG67007; TNNT3, Id: COSG60869) are overexpressed in several cancer types according to the COSMIC database." (PMID 29416706, 2018). "Additional research reveals that Tnnt1 strongly activates the p38/JNK signaling pathway, which, when aberrantly activated, contributes to excessive cell proliferation and reduced apoptosis, thereby facilitating the progression, migration, and invasion of various cancers." (PMID 41127012, 2025).
myopathy (10 papers, 2013 to 2025). A disease of the muscle in which the muscle fibers do not function properly. "Our identification of the causative mutation in TNNT1 makes the OCPMD sheep an attractive large animal model for better understanding the pathobiology of human TNNT1 myopathy." (PMID 32819427, 2020). "The increasing application of genetic screening is anticipated to identify more TNNT1 myopathy mutations." (PMID 27790152, 2016). "TNNT1 myopathies are featured by loss of slow twitch muscle fibers and presented with severe muscle atrophy, weakness and failure of respiratory muscle." (PMID 28018233, 2016). "As a result, four more truncation or internal deletion mutations in TNNT1 gene have recently been reported in multiple other ethnic groups around the world to cause myopathies similar to that of ANM." (PMID 27790152, 2016). "The identification and mechanistic studies of the Amish NM (ANM) have raised clinical awareness and the inclusion of testing for TNNT1 mutations in the diagnosis of myopathies." (PMID 27790152, 2016). "Interestingly, the loss of function of TNNT1 in a mouse model produced a myopathy in animals carrying mutation in this gene." (PMID 41117889, 2025). "The characterization of ANM called for TNNT1 genetic testing in the diagnosis of myopathies, and numerous other mutations have been reported in TNNT1 gene to cause recessive or conditionally dominant myopathies with progressive muscle deteriorations." (PMID 34733179, 2021). "First, we reported 18 novel variations in 6 myopathy-causing genes, including RYR1, NEB, ACTA1, DNM2, TTN and TNNT1, and we described the clinical discrepancy between our patients and previous reports, especially in RYR1- and TNNT1- related myopathy." (PMID 35081925, 2022). "The first TNNT1 myopathy identified was Amish nemaline myopathy (ANM), a lethal recessive nemaline myopathy affecting approximately 1 in 500 births in the Amish communities in Pennsylvania and Ohio." (PMID 34733179, 2021). "The identification of ANM and subsequent mechanistic studies have promoted clinical awareness of TNNT1 myopathy and its testing in the clinical diagnosis of myopathies." (PMID 27790152, 2016). "The expression of CAIII in Tnnt1-KO myopathy mouse soleus muscle that has diminished slow fiber contents due to the loss of slow troponin T remained high." (PMID 28018233, 2016). "Therefore, it would be worth further investigating whether the haploid insufficiency in carriers of these recessive TNNT1 myopathies may cause conditional slow TnT deficiency with symptoms such as experiencing conditional fatigue intolerance and other slow muscle-related dysfunctions." (PMID 27790152, 2016). "The expression of CAIII in Tnnt1-KO myopathy mouse soleus muscle that has diminished slow fibers remained high." (PMID 28018233, 2016). "However, a relevant human case of TNNT1 nemaline myopathy describes a compound heterozygous splice site change (resulting in exon 8 deletion) and an exon 14 deletion in a Dutch pedigree." (PMID 32819427, 2020). "The data suggest a fiber type independent expression of CAIII with a role in the regulation of intracellular pH in skeletal muscle and may be explored as a target for improving fatigue resistance and for the treatment of TNNT1 myopathies." (PMID 28018233, 2016). "The expression of CAIII was examined in soleus muscle of WT and Tnnt1-KO myopathy mice." (PMID 28018233, 2016). "The observation that only a few mouse fast fiber muscles are lack of CAIII, such as EDL, tongue and masseter, suggests that an increase in the level of CAIII may be explored as an anti-fatigue treatment for TNNT1 myopathies." (PMID 28018233, 2016). "Therefore, we hope this focused review will benefit readers with the vision beyond TNNT1 myopathy studies." (PMID 27790152, 2016).
myopathy (continued). "It is worth noting that the slow isoform of TnI remains detectable in Tnnt1-KO soleus muscle, indicating a maintained slow muscle tissue environment that may play a role in sustaining CAIII expression and a plausible foundation for exploring new treatment of TNNT1 myopathies." (PMID 28018233, 2016). "The genes DES, TNNT1, MYH7, and DYSF were identified as important regulatory genes in both the OMIM and KEGG myopathy pathway." (PMID 40149400, 2025). "Several genes were found to be significantly enriched by simvastatin treatment in primary human muscle cells and were mapped to both OMIM as well as KEGG pathways for myopathy, including DES, TNNT1, MYH7, and DYSF." (PMID 40149400, 2025). "TNNT1 myopathies are, therefore, no longer considered as an isolated disease of the Amish, but are of increasing medical importance." (PMID 27790152, 2016).
cardiovascular disease (2 papers, 2015 to 2018). "However, most studies on TNNT1 are about its function in cardiovascular diseases, whether it is involved in tumorigenesis is rarely known." (PMID 25970782, 2015).
musculoskeletal disorders (1 paper, 2024). "We observed that MYH7, RYR1, FBN1, TNNT1, MYBPC1, COL1A1, and CHRNB1 were related to musculoskeletal disorders." (PMID 38658807, 2024).
TNNT1 also shares sentences with these, for which no sentence is quoted: centronuclear myopathies (2 papers); papillary thyroid carcinoma (2); acute coronary syndrome (1); astrocytoma (1); atherosclerosis (1); cardiac arrhythmia (1); Charcot-Marie-Tooth disease type 1 (1); colon adenocarcinoma (1); congenital nemaline myopathy (1); dermatomyositis (1); dilated cardiomyopathy (1); distal arthrogryposis (1); Duchenne muscular dystrophy (1); endometrioid adenocarcinoma (1); genetic diseases (1); glioma (1); glycogen storage disease (1); leiomyosarcoma (1); malignant mesothelioma (1); mastitis (1); mesothelioma (1); muscular disease (1); muscular dystrophy (1); Myotonia (1); neuropathy (1); ovarian carcinoma (1); peritoneal effusions (1); polymyositis (1); respiratory failure (1); rhabdomyosarcoma (1).
A further 1 disease shares a sentence with TNNT1 in 1 paper.